TCF3 (transcription factor 3)
Diseases named in the same sentence as TCF3 in open-access papers (continued):
Sharing a sentence is not in itself a finding about the gene and the disease.
renal fibrosis (2 papers, 2022 to 2025). A final common manifestation of a wide variety of chronic kidney diseases characterized by glomerulosclerosis and tubulointerstitial fibrosis. "Our findings establish a novel TCF3-Netrin-1-autophagy regulatory axis that contributes to renal fibrosis in experimental DN models." (PMID 41404576, 2025). "This study addresses the fundamental question of whether targeting TCF3 represents a viable therapeutic strategy for preventing renal fibrosis in DN." (PMID 41404576, 2025). "While our findings are limited to experimental models and lack human tissue validation, they identify TCF3 as a promising therapeutic target for preventing renal fibrosis in DN through autophagy restoration, pending the development of specific pharmacological inhibitors." (PMID 41404576, 2025). "Nephronophthisis 4 (NPHP4), transcription factor 3 (TCF3), and IQ motif and Sec7 domain 1 (IQSEC1) were found to be involved in pathways that promote the epithelial to mesenchymal transition and renal fibrosis." (PMID 35806113, 2022).
schizophrenia (2 papers, 2020 to 2024). A major psychotic disorder characterized by abnormalities in the perception or expression of reality. "In sum, HAND1::TCF3 target genes with neural-cardiac roles provide a means to elucidate the genetic causes of comorbidity between schizophrenia and cardiovascular diseases." (PMID 38167462, 2024). "The 105 schizophrenia-associated HC ELEs show strong enrichments of motifs recognized by POU3F3 and HAND1::TCF3 complex, all of which are relevant to schizophrenia." (PMID 38167462, 2024). "Several genes were validated in APA sperm that were associated with autism spectrum disorder (CACNA1H, CNTNAP2, GRIN1, SHANK2, SHANK3, ZNF804A), schizophrenia (TCF3, ZNF804A), and bipolar disorder (COMT, DRD4, GRIN1, MBP, PRKCZ, SHANK2, TRPM2, ZNF804A), and in APA blastocysts (CACNA1H)." (PMID 32610362, 2020).
thymoma (2 papers, 2022 to 2024). A neoplasm arising from the epithelial cells of the thymus. "TCF3 demonstrated the most pronounced correlation with heterogeneity in UVM, but in thymoma (THYM), the correlation was inversely related." (PMID 39205642, 2024). "In contrast, levels of nuclear inhibitors were variably higher in thymomas and TCs than in NTs: TLE2 and TCF4 were significantly (p <0.01) higher in B3 thymomas and TCs, TLE4 only in B3 thymomas and TCF3 only in AB thymomas." (PMID 35965500, 2022).
uveal melanoma (2 papers, 2024 to 2025). A melanoma derived from melanocytes of the uveal tract. "TCF3 holds promise as a molecular marker for diagnosis and as a potential target for novel therapeutic strategies, particularly in uveal melanoma." (PMID 39205642, 2024).
AA amyloidosis (1 paper, 2025). Secondary amyloidosis is a form of amyloidosis, that complicates chronic inflammatory disorders (mainly rheumatoid arthritis) and is characterized by the aggregation and deposition of amyloid fibrils composed of serum amyloid A protein, an acute phase reactant. "Dysimmune complications (severe autoimmune enteropathy) and AA amyloidosis in a patient with TCF3 mutation and septic choc in two patients without genetic confirmation, were the causes of death." (PMID 40703516, 2025).
acute promyelocytic leukemia (1 paper, 2025). An aggressive form of acute myeloid leukemia (AML), characterized by arrest of leukocyte differentiation at the promyelocyte stage, due to a specific chromosomal translocation t(15;17) in myeloid cells. "All-trans retinoic acid can achieve therapeutic effects in acute promyelocytic leukemia (APL) cell lines and primary patient cells by rapidly increasing ID1 expression and downregulating TCF3, leading to G0/G1 cell-cycle arrest." (PMID 41146039, 2025).
Anophthalmia (1 paper, 2018). Absence of the globe or eyeball. "A single tcf3 gene exists in the medaka genome and its inactivation strongly affected eye development of the embryos, leading to size reduction and anophthalmia in severe cases." (PMID 29316906, 2018).
autoimmune lymphoproliferative syndrome (1 paper, 2017). Autoimmune lymphoproliferative syndrome (ALPS) is a rare, inherited disorder characterized by non-malignant lymphoproliferation, multilineage cytopenias, and a lifelong increased risk of Hodgkin's and non-Hodgkin's lymphoma. "We did also report a novel form of autoimmune lymphoproliferative syndrome caused by homozygous FAS mutations with normal or residual protein expression as well as a novel AR transcription factor 3 deficiency." (PMID 28702026, 2017).
Azoospermia (1 paper, 2021). Absence of any measurable level of sperm,whereby spermatozoa cannot be observed even after centrifugation of the semen pellet. "Moreover, the level of TCF3 protein was remarkably lower in patients with spermatogenesis failure when compared to individuals with obstructive azoospermia with normal spermatogenesis." (PMID 34422820, 2021). "In addition, we revealed that TCF3 levels were remarkably decreased in NOA patients compared to individuals with obstructive azoospermia (OA) with normal spermatogenesis, particularly in the NOA patients with spermatogonial or spermatocytes maturation arrest (Spc MA)." (PMID 34422820, 2021).
biliary tract cancer (1 paper, 2024). "Mutational analysis of TCF3 across diverse cancer types reveals the highest alteration rates in biliary tract cancer." (PMID 39205642, 2024). "The results showed that TCF3 had the highest alteration frequency in biliary tract cancer, and deep deletions accounted for almost the entire proportion of alterations." (PMID 39205642, 2024).
breast tumours (1 paper, 2013). "Taken together, these results suggest TCF3 as a new marker of basal-like breast tumors and support the interplay between E47 and ID factors in this tumour subtype." (PMID 23555842, 2013). "Importantly, our present study detected TCF3 upregulation in basal-like tumours in several additional public datasets and associated to poor survival, reinforcing previous observations indicating that basal-like carcinomas are the most likely candidate breast tumours to suffer EMT processes." (PMID 23555842, 2013). "Upregulation of Id4 transcripts were also previously observed in MDCK cells overexpressing E47, although to a lower extent than Id1, supporting also the correlation between ID4 and TCF3 upregulation in basal breast tumours." (PMID 23555842, 2013).
cardiac hypertrophy (1 paper, 2023). "Finally, mice deficient in Atf3 which encodes transcription factor 3 (ATF3), a partner protein of FOS, exhibited fibrosis and cardiac hypertrophy in response to pressure overload, suggesting an important transcriptional role for Atf3 in the cardiovascular system." (PMID 36736425, 2023).
chondrosarcoma (1 paper, 2009). A malignant cartilaginous matrix-producing mesenchymal neoplasm arising from the bone and soft tissue. "TCF3 is translocated to a number of fusion partners in pre- and pro-B-ALL, while TCF12 is fused to NR4A3 in extraskeletal mixoid chondrosarcoma." (PMID 19461887, 2009).
CNS leukemia (1 paper, 2024). "Moreover, 50% of the relapsed children had BCR::ABL1 or TCF3:: PBX1 fusion genes as a high-risk factor for CNS leukemia relapse, consistent with literature reports." (PMID 38519960, 2024).
colon adenocarcinoma (1 paper, 2024). "The results showed that the SNV frequencies of TCF4, TCF3, and TCF7 were highest in UCEC (42% for TCF4, 14% for TCF3 and TCF7), followed by skin cutaneous melanoma (SKCM) (38% for TCF4, 10% for TCF3, and 4% for TCF7) and colon adenocarcinoma (COAD) (13% for TCF4, 10% for TCF3, and 8% for TCF7)." (PMID 39205642, 2024).
colorectal tumors (1 paper, 2014). "We, herein, provide the evidence showing methylation of TCF3 is a common event in colorectal tumors." (PMID 25375219, 2014).
diabetic nephropathy (1 paper, 2025). "To further investigate the regulatory role of TCF3 in autophagy, we examined the expression of proteins associated with the PI3K/Akt/mTOR signaling pathway in renal tissues of diabetic nephropathy rats via Western blotting." (PMID 41404576, 2025).
fatty liver (1 paper, 2024). "Moreover, dietary genistein had the potential to directly alleviate the inflammatory response by modulating the expression of inflammatory factors such as NF-кB, IL-8, IL-1β, and IFN-γ through the involvement of PPARδ and T-cell factor 3 (TCF3) in laying hens induced fatty liver." (PMID 38540097, 2024).
gastric tumor (1 paper, 2022). "Hence, it seems that the binding efficacy of miRNAs to the 3′-UTR of the TCF3 gene is not the only determinant in breast and gastric tumor development." (PMID 34700372, 2022).
infertile (1 paper, 2025). "However, previous work has demonstrated that TCF3 deficiency is associated with spermatogenesis failure in infertile human patients." (PMID 40086448, 2025).
ischemic stroke (1 paper, 2025). A stroke disorder caused by obstruction of blood flow to the brain, due to thrombotic (local blood clot formation) or embolic (due to a blood clot or other material traveling from another site) event. "This study aimed to investigate the role of activating transcription factor 3 (ATF3) in ischemic stroke and mitochondrial homeostasis." (PMID 40621504, 2025).
latent infection (1 paper, 2024). "Moreover, actively proliferating cell subsets in early and latent infection contexts have EZH2, TCF3, and BRCA1 expression signatures as observed in proliferating DZ B cells in vivo." (PMID 38059622, 2024).
liver fibrosis (1 paper, 2017). "Plumbagin inhibits liver fibrosis by decreasing the expression of epidermal growth factor receptor (EGFR) and transcription factor 3 (STAT3) in the liver." (PMID 28770223, 2017).
lymphoid leukemia (1 paper, 2015). A malignant lymphocytic neoplasm of B-cell or T-cell lineage involving primarily the bone marrow and the peripheral blood. "Our ChIP-seq analysis of TRIM33 in myeloid, B lymphoid, and T lymphoid leukemias suggests that other TFs are also likely to recruit TRIM33, such as TCF3/E2A." (PMID 25919951, 2015).
male infertility (1 paper, 2021). The inability of the male to effect fertilization of an ovum after a specified period of unprotected intercourse. "Thus, it would be interesting to establish animal models to further determine whether the deficiency of TCF3 will cause spermatogenesis failure and male infertility." (PMID 34422820, 2021).
multiple sclerosis (1 paper, 2021). A progressive autoimmune disorder affecting the central nervous system resulting in demyelination. "TCF3 is involved in lymphocyte development, and TCF7L2 has been implicated in neural development and diseases, such as multiple sclerosis, where a role in demyelination and remyelination has been suggested." (PMID 34946971, 2021).
neuroendocrine neoplasm (1 paper, 2021). Endocrine tumors, also referred to as neuroendocrine tumors (NETs), are defined by a common phenotype which is characterized by the expression of general markers (neuron specific enolase, chromogranin, synaptophysin) and hormone secretion products. "Our data suggest that transcription factor 3/HNF1A-AS1/Oncostatin M axis inhibits the tumorigenesis and metastasis of gastroenteropancreatic neuroendocrine neoplasms via transforming growth factor-β signaling." (PMID 34037532, 2021).
peripheral nerve injury (1 paper, 2021). Injury to a peripheral nerve. "Peripheral nerve injury downregulates DS‐lncRNA in injured DRG due, in part, to silencing of POU domain, class 4, transcription factor 3, a transcription factor that interacts with the DS‐lncRNA gene promoter." (PMID 34383386, 2021).
premature ovarian failure (1 paper, 2017). "For example, decreased functional interaction between Figla and Tcf3 in human could cause premature ovarian failure." (PMID 28151980, 2017).
prostate tumor (1 paper, 2017). "In particular, we found primarily overexpression of CTNNB1, CDH1, SMAD2, SMAD3, TCF3, LEF1 in younger patients and overexpression of SNAI1 and underexpression of KRT5, KRT19, OCLN, CDH2 and MUC1 which clearly indicates different characteristics of prostate tumor in younger vs older patients." (PMID 29206234, 2017).
pulmonary hypertension (1 paper, 2021). Increased pressure within the pulmonary circulation due to lung or heart disorder. "In addition, in pulmonary hypertension, researchers found that exosomes can ease pulmonary remodeling and reduce pulmonary hypertension by inhibiting high value-added pathways such as transcription factor-3 and inhibiting inflammation of monocytes." (PMID 34360530, 2021).
rectal cancer (1 paper, 2016). A primary or metastatic malignant neoplasm that affects the rectum. "Additionally, previous literature has revealed that TCF3 and TCF4 are overexpressed in rectal cancer and they control MYC expression in colorectal cells." (PMID 27818995, 2016).
renal cell carcinoma (1 paper, 2019). "Other EMT regulators, such as Zeb1, Zeb2, and TCF-3, have been reported to be upregulated in pVHL-null renal cell carcinoma in which HIF-1α is constitutively overexpressed." (PMID 30696468, 2019).
Renal insufficiency (1 paper, 2021). A reduction in the level of performance of the kidneys in areas of function comprising the concentration of urine, removal of wastes, the maintenance of electrolyte balance, homeostasis of blood pressure, and calcium metabolism. "A Renal Insufficiency Cohort (CRIC) identifies enhanced DNA methylation in genes of IQ motif and Sec7 domain 1 (IQSEC1), nephronophthisis 4 (NPHP4), and transcription factor 3 (TCF3) in participants with stable renal function while compared to those with rapid loss of eGFR." (PMID 33737884, 2021).
retinoblastoma (1 paper, 2024). A malignant tumor that originates in the nuclear layer of the retina. "The right panel represents the correlation between TCF3 expression and angiogenesis score in retinoblastoma (RB) using Pearson’s analysis, indicating a markedly positive association between TCF3 expression and angiogenesis hallmarks in RB." (PMID 39205642, 2024).
rhabdomyosarcoma (1 paper, 2010). A rare aggressive malignant mesenchymal neoplasm arising from skeletal muscle. "MYOD1 has been recently implicated in myoblast maintenance, and, in combination with TCF3, it inhibits myoblast differentiation leading to Rhabdomyosarcomas." (PMID 20500816, 2010).
schwannoma (1 paper, 2024). A benign, usually encapsulated slow growing tumor composed of Schwann cells. "Integrated single-nuclei and single-cell RNA sequencing showed TCF3 target genes were expressed in schwannoma cells from human tumors, and schwannoma clustering restricted to RNA sequencing of TCF3 target genes recapitulated neural crest and immune-enriched molecular groups of schwannomas." (PMID 38216587, 2024).
silicosis (1 paper, 2024). Silicosis is a respiratory disease caused by breathing in (inhaling) silica dust. "Transcription factor 3, an inflammatory repressor, can be activated for early diagnosis of silicosis." (PMID 39866352, 2024).
testis cancer (1 paper, 2024). "TCF3 showed an overall upwards trend in tumor tissues, with the most significant increase observed in testis cancer, uterine carcinosarcoma, and uterine endometrial carcinoma." (PMID 39205642, 2024).
thyroid carcinoma (1 paper, 2024). "In kidney papillary cell carcinoma and liver hepatocellular carcinoma, TCF3 levels were increased, whereas decreased expression of TCF3 was observed in thyroid carcinoma." (PMID 39205642, 2024).
type 1 diabetes (1 paper, 2017). "Her symptomatic son, who has inherited only the TCF3 mutation, but not the TACI gene mutation, has type 1 diabetes (T1D), synovitis, reduced IgG levels and IgA deficiency." (PMID 29114388, 2017).
tumor (81 papers, 2001 to 2025). "ov-TCF3 led to a notable rise in tumor volume, weight, and levels of TMBIM6 and GPX4, while causing a significant decrease in tumor Ca2+ concentration." (PMID 40610429, 2025). "Surprisingly, the overexpression of SEH1L and TCF3 was associated with vice versa high sensitivity of tumor cells to these compounds." (PMID 41153808, 2025). "In previous studies, TCF3 has been shown to be associated with tumor development in many other cancer species, however, little is known about the role of TCF3 in ESCC." (PMID 37607071, 2023). "Based on the mRNA expression profile of GC tumor and adjacent normal tissues from the GSE13861 and GSE54129 cohorts, FEN1, PDGFRB, SERPINE1, and TCF3 were up-regulated in tumor tissues, which coincide with their risk roles in the senescence-related signature." (PMID 37100457, 2023). "Of note, Ikzf1, Spi1, Tcf3, and Pax5 are normally expressed in induced B cell progenitors, which ensure tumor-free lymphopoiesis as reduction or loss of any of these master factors is associated with B cell leukemia." (PMID 34893754, 2022). "TCF3 encodes an important TF involved in lymphopoiesis, including B-cell development, operating as a tumor suppressor in this entity." (PMID 36233173, 2022). "TCF3 is known to have two splice variant products, E12 and E47, which can act as either oncoproteins or tumor suppressors in a context-dependent manner." (PMID 34175897, 2021). "Strikingly, significant reductions in Ebf1, Tcf3 (encoding E2A), and Runx1 transcripts were observed in tumor compared to unaffected EB cells." (PMID 28692033, 2017). "Besides, TCF3 knockdown partially restored tumor growth restriction caused by TRIM21 downregulation in vivo, and the corresponding results of IHC staining were also obtained." (PMID 40998798, 2025). "TCF3 may promote tumor-associated pathologic angiogenesis, reshape the oxygen-depleted immune-cold tumor microenvironment, and significantly predict poor prognosis and unfavorable responses to VEGF-TKI therapy in patients with cancer, notably in KIRC and UVM." (PMID 39205642, 2024). "TCF-3 has been implicated in diverse aspects of tumor development." (PMID 39205642, 2024). "As a transcriptional repressor of E-cadherin, TCF3 implicated in epithelial to mesenchymal transition and may be linked to tumor aggressiveness." (PMID 25375219, 2014). "In this study, we present the first comprehensive characterization showing that SE-driven TRIB2 expression is mediated through tumor-specific E-P looping, with TCF3 acting as an activator of this mechanism to drive HB pathogenesis." (PMID 41462308, 2025). "We observed that overexpression of TCF3-18B (E47) isoform led to a significant increase in invasive potential of both MCF7 and MDA-MB-231 cells indicating that TCF3-18B (E47) isoform of TCF3 gene promotes tumor cell invasion." (PMID 41150697, 2025). "In vivo, ov-TCF3 promoted tumor volume, weight, and TMBIM6 expression, and inhibited Ca2+ concentration, while Erastin reversed these changes." (PMID 40610429, 2025). "Using this resource, we compared the relative ratio of TCF3-exon 18a/18b inclusion in normal and tumor tissues." (PMID 40766465, 2025). "TCF3, which is a crucial transcription factor in the Wnt pathway, modulates various downstream genes involved in tumor differentiation." (PMID 41390817, 2025). "PTBP1 helps in exon 18A exclusion under hypoxia resulting in the production of the TCF3-18B containing E47 isoform which helps tumor cell invasion under hypoxia." (PMID 41150697, 2025). "Focusing next on 33 solid tumor types, most demonstrated similar levels of TCF3-exon 18a and exon 18b inclusion, but several tumor types exhibited a greater than 10% difference in the ratio of inclusion for these mutually exclusive exons." (PMID 40766465, 2025). "From an academic standpoint, progress in understanding TCF3 and its effects on tumor biology has revealed its potential clinical value and implications for therapeutic interventions." (PMID 39205642, 2024).